PRC1 (protein regulator of cytokinesis 1)
Diseases named in the same sentence as PRC1 in open-access papers (continued):
Sharing a sentence is not in itself a finding about the gene and the disease.
cancer (continued). "As in the case of PRC2, increased expression and activity of PRC1 components is also a common hallmark of multiple human cancers." (PMID 26580594, 2015). "Protein regulator of cytokinesis 1 (PRC1) and the guanine nucleotide exchange factor, Ect2, the two major molecules of cytokinesis have been related with cancer-associated altered expressions and CIN." (PMID 25999914, 2015). "In summary, MLL/COMPASS and PRC2 promote a hypomethylated state, particularly focused on promoters and CGI, while PRC1 promotes DNA hypermethylation; promoters where this interplay occurs are susceptible to aberrant DNA hypermethylation in human cancers." (PMID 25071008, 2014). "The dysregulation of PRC1 has been associated with the initiation and progression of human cancers." (PMID 40405133, 2025). "Besides, the overexpression of the PCGF1 subunit of the PRC1 in cancer stem cells has been associated with an enhanced expression of CD133." (PMID 38956727, 2024). "With the identification of specific PRC1 variants at a large number of active loci, it is now accepted that the presence of Polycomb subunits does not always correlate with transcriptional repression states, especially in cancer cells." (PMID 35362516, 2022). "Like PRC2, PRC1 components are widely implicated in many types of cancers." (PMID 35046519, 2022). "Indeed, cancer-related DNA demethylation of satellite II at 1q12 is responsible for the recruitment of PRC1 to cancer-associated polycomb (CAP) bodies, and this leads to derepression of other satellite II DNA loci." (PMID 32481609, 2020). "The Polycomb Repressive Complex 1 (PRC1) is a chromatin-associated protein complex involved in transcriptional repression of hundreds of genes controlling development and differentiation processes, but also involved in cancer and stem cell biology." (PMID 32230868, 2020). "BMI1, encoding for PCGF4, is the best studied PRC1 gene in cancer to date." (PMID 30139998, 2018). "Because reconfiguration of chromatin remodeling complexes may provide new opportunities to uncover epigenetic vulnerabilities, we interrogated the DepMap database of cancer dependencies for SyS-selective vulnerability to inactivation of any of the six PRC1 variants." (PMID 33361335, 2021). "Through GSEA single gene differential analysis, we determined that PRC1 was related to cancer immunotherapy (left) and programmed cell death (PCD) (right)." (PMID 40847353, 2025). "CBX4, a pivotal component of the PRC1, plays multifaceted roles in cancer development and progression." (PMID 40740235, 2025). "Next, we investigated the expression levels of PRC1 in ccRCC cancer cell lines and normal renal tubular epithelial cell line HK-2." (PMID 40093809, 2025). "Canonical PRC1 represses expression of tumor suppressor genes (e.g., p16Ink4a, p19Arf) through histone ubiquitination and BMI1, a core component of PRC1, is upregulated in various types of cancers." (PMID 40599851, 2025). "The PRC1 complex subunits exhibit a multitude of functions, including the regulation of anoikis, cancer cell stemness, and tumor progression." (PMID 39793896, 2025). "By focusing on epigenetic alterations, particularly PRC1/Bmi‐1 deregulation, our present review does address a crucial and emerging area of cancer research, highlighting the significance of epigenetic factors in GBM pathogenesis." (PMID 39791545, 2025). "The interplay of CBXs within the PRC1 significantly impacts cancer growth through complex regulatory mechanisms." (PMID 40175347, 2025). "Growing evidence reveals that PRC1 presents ectopic expression in some malignant tumors and involves in malignant progression of human cancers." (PMID 40847353, 2025). "CBX4 encodes a component of the PRC1 and also functions as a SUMO E3 ligase, implicating it in chromatin modification and post-translational regulation, both of which are critical in cancer development." (PMID 40740235, 2025).
cancer (continued). "To date, both RING1B inhibitors and PRC1 degraders have been developed and tested in various human cancer cell line models." (PMID 39817454, 2025). "RYBP is a key interaction partner of YY1, and it is also a component of the Polycomb repressive complex 1 (PRC1), a well-known chromatin-modifying complex that monoubiquitinates histone H2A, thus repressing gene expression during development and in cancer." (PMID 40867231, 2025). "The components of PRC1 are deregulated in multiple cancers, and their dysfunction is responsible for proliferation and antiapoptosis." (PMID 39793896, 2025). "Recurrent sites of aDMRs showed an enrichment for PRC1 and two binding sites, congruent with their well-known role in stem cell regulation and cancer." (PMID 39406235, 2024). "The overexpression of PRC1 was related to cell proliferation and drug resistance in cancer cells, resulting in poor prognosis." (PMID 39409930, 2024). "In the last decade, the PRC1 complex has been intensively investigated to screen its precise role in chromatin remodeling and other cell events including cancer." (PMID 39337298, 2024). "To further validate the clinical significance of PRC1, we utilized the UALCAN database, analyzing PRC1 expression across different demographics and clinical factors, such as gender, age, metastatic status, cancer stage, and cancer grade." (PMID 39409930, 2024). "Silencing PRC1 expression using siRNA significantly inhibited cancer cell proliferation and viability and increased chemotherapeutic drug sensitivity." (PMID 39409930, 2024). "PRC1 exerts oncogenic effects by promoting cancer proliferation, stemness, metastasis, and tumorigenesis." (PMID 39596041, 2024). "On the other hand, “epi-drugs” targeting PRC1 can also potentially transform healthy tissues into epigenetically initiated cancers and induce genome instability in response to protracted treatments." (PMID 38888809, 2024). "PRC1 promotes cancer cell proliferation and has been identified as a potential therapeutic target for several cancers, including lung and ovarian cancer." (PMID 39409930, 2024). "B cell‐specific Moloney murine leukemia virus Integration site 1 (BMI1) and really interesting new gene 1B (RING1B) are PRC1 core components and play critical roles in the development of various cancers." (PMID 36737841, 2023). "Overall, this study provides a novel BMI1/RING1B degrader, which is a useful chemical tool to further investigate the roles of PRC1 in cancer, and a novel protein complex degradation strategy, which can potentially expand the degradable human proteome." (PMID 36737841, 2023). "PRC1 and 2 are major regulators of epigenetic silencing in developmental processes and pathologies including cancer and inflammatory diseases and are involved in the control of intestinal crypt homeostasis and regeneration after damage." (PMID 36639541, 2023). "PRC1, a prominent epigenetic protein complex, plays critical roles in cancer development and progression." (PMID 36737841, 2023). "Bmi-1 is a master regulator of stem cell self-renewal as part of the polycomb repressive complex 1 (PRC1) and has emerged as a prominent player in cancer stem cell biology." (PMID 36726797, 2023). "The protein regulator of cytokinesis 1 (PRC1) is an essential gene for cytokinesis and is involved in cancer pathogenesis." (PMID 35983074, 2022). "For example, glucose deprivation-induced inactivation of PRC1 (polycomb-repressive complex 1) promotes ER (endoplasmic reticulum) stress and cell death, leading to the strategic combination of PRC1 inhibitor and GLUTi treatment in cancer cells." (PMID 35178349, 2022).
cancer (continued). "The PcG proteins play a critical role in the progression of cancer forming multimeric complexes involved in transcriptional repression, including Polycomb repressive complex 1 (PRC1) and Polycomb repressive complex 2 (PRC2)." (PMID 36076977, 2022). "“Proliferative CAFs” in Branch 5 specifically expressed PRC1, a mitotic spindle-associated protein, and Aurora A kinase (encoded by AURKA), both of which are known to promote cancer cell proliferation and tumor growth." (PMID 35884546, 2022). "Knockdown or knockout of PRC1 inhibited the growth, metastasis, recurrence, and/or drug resistance of various cancers." (PMID 35983074, 2022). "PCGF4 (also known as BMI-1), the best-studied PRC1 gene in cancer, was one of the first PcG genes found in mammals and has been defined as a proto-oncogene that cooperates with the c-Myc oncoprotein to promote tumorigenesis." (PMID 36076977, 2022). "As a core element of polycomb repressive complex 1(PRC1), BMI1 has been found to be associated with various human cancers and become an attractive therapeutic target." (PMID 36199791, 2022). "In order to find the PRC1 components involved in TGF-β-induced EMT of cancer cells, we tried to perform a candidate gene approach." (PMID 33779563, 2021). "Global DNA hypomethylation and PRC1 localization to the chromocenter have been reported in pre-implantation embryos and cancer cells." (PMID 34166371, 2021). "The results indicated that PRC1 expression was significantly higher in cancer tissues than that in normal tissues (P < 0.001)." (PMID 33292244, 2020). "Recently, it was reported that the CDK16/CCNY complex increased the proliferation of several cancer cell lines through the phosphorylation of the protein regulator of cytokinesis 1 (PRC1)." (PMID 31420702, 2020). "ESC hiBiv CGIs, enriched in canonical PRC1 components and much reduced H3K4me3, that are preferentially hypermethylated in cancer add clarity to this process." (PMID 32131813, 2020). "The Pc/CBX family member proteins are components of the canonical PRC1 protein complex that maintain transcriptional repression of hundreds of genes involved in development, differentiation, signaling or cancer." (PMID 32230868, 2020). "Another article found that CBX2 is also the only CBX protein with a DNA binding domain 37, which is associated with modulating transcription of target genes and binding to other PRC1 components and is involved in the development of human cancer." (PMID 32742466, 2020). "In cancer cells, the expression pattern of protein regulators included in cell cycle and apoptosis progress were reverted by PRC1 down-regulation." (PMID 33292244, 2020). "Protein regulator of cytokinesis 1 (PRC1) has been reported to play important role in the pathogenesis of various cancers." (PMID 33292244, 2020). "BMI1 is a core protein of the polycomb repressive complex 1 (PRC1) that is overexpressed in several cancer types, making it a promising target for cancer therapies." (PMID 32343689, 2020). "PRC1 downregulation decreased cell viability in all tested cancer cell lines except for HeLa cells, whereas CDK16 downregulation decreased cell viability in all cell lines." (PMID 30992425, 2019). "Numerous studies have shown that PRC1 and TOP2A play roles in multiple cancers and extensive studies have shown that PRC1 is involved in cell cycle processes." (PMID 31737106, 2019). "Chromobox 6 (CBX6) is a subunit of Polycomb Repressive Complex 1 (PRC1) that mediates epigenetic gene repression and acts as an oncogene or tumor suppressor in a cancer type-dependent manner." (PMID 30655550, 2019).
cancer (continued). "Altered expression and mutation of PRC1 has been linked to human carcinogenesis, while CDK16 is essential for the proliferation of some types of cancer cells." (PMID 30992425, 2019). "The enzymatic subunit or “writer” of PRC1, BMI-1, is considered to play a role in malignant transformation of multiple cancers, including ovarian cancer." (PMID 30478317, 2018). "It is therefore possible that the aberrant expression of PRC1 in cancer cells leads to defects in mitotic exit, thereby contributing to CIN and aneuploidy, which can trigger tumorigenesis." (PMID 29435157, 2018). "Since the first discovery of RYBP in 1999, there has been marked progress in understanding its functions in physiological and pathological conditions, including embryonic development, apoptosis and cancer, as well as its role as a component of PRC1." (PMID 29383875, 2018). "PRC1 and 2 epigenetically repress pro-differentiation and tumor suppressor genes, and are important in several cancer types including prostate, breast, and HGSOC10,11." (PMID 30478317, 2018). "In this study, we now report a similar dependency of lung tumorigenesis on PRC1, consistent with previous studies that have provided evidence for a role of PRC1 in different types of cancer." (PMID 29435157, 2018). "H3K27me3 is a hallmark of transcriptional silencing and is thought to result in gene repression together with PRC1, which play important roles in cancer." (PMID 29212262, 2017). "For this reason, it seems unlikely that the induction of CDKN2A and CDKN2B expression observed in both these cancers is related to a reduction in expression of the BMI1 component of PRC1." (PMID 29069809, 2017). "PRC1 has been linked to the repression of certain tumor suppressor genes, such as PTEN and INK4a/ARF (CDKN2A), in carcinoma cells." (PMID 29050200, 2017). "High levels of the PRC1 components Bmi1 and Ring1b and the strong repression of differentiation genes in 3D-ADMs and cancer cells let us suppose that PRC1 is directly involved in acinar gene regulation." (PMID 26716510, 2016). "More recently, miRNA-181a was established as a direct regulator of RING2 (PRC2) and CBX7 (PRC1) in cancer." (PMID 24217920, 2014). "BMI1 is a member of the PRC1 complex; it controls many diverse biological cancer processes including differentiation, senescence, proliferation, migration, and tumorigenesis." (PMID 23820733, 2013). "Bmi1 is a key component of PRC1 regulating chromatin remodeling and gene expression pathways essential for self-renewal of stem cells and cancer stem cells." (PMID 19956605, 2009). "The identification of an Ubq-like domain in the PRC1 Ring family offers new experimental approaches aimed at elucidating their roles in important cellular processes, such us, stem cell self-renewal and cancer." (PMID 18588675, 2008). "In both mouse embryonic stem cells and human cancer cell lines, the transcriptional defect induced by BAP1 depletion or catalytic-inactive mutations could be fully rescued by PRC1 depletion." (PMID 39817454, 2025). "Specifically, a 24-h transient downregulation of polyhomeotic (ph-KD), a core component of the Polycomb complex PRC1, is sufficient to induce epigenetically initiated cancers (EICs) in Drosophila, which are proficient in DNA repair and characterized by a stable genome." (PMID 38888809, 2024).
cancer (continued). "Here we show that prolonged depletion of a PRC1 component, which mimics cancer initiating events, results in broad dysregulation of DNA replication and repair genes, along with the accumulation of DNA breaks, defective repair, and widespread genomic instability in the cancer tissue." (PMID 38746379, 2024). "Bmi-1 promotes cancer stemness not only as a subunit of PRC1 but also in a PRC1-independent manner." (PMID 38141761, 2024). "Specifically, a 24-hours transient down-regulation of polyhomeotic (ph-KD), a core component of the Polycomb complex PRC1, is sufficient to drive epigenetically initiated cancers (EICs) in Drosophila, which are proficient in DNA repair and are characterized by a stable genome." (PMID 38746379, 2024). "Here, we investigate whether a sustained inactivation of PRC1, which mimics a cancer-inducing context, eventually results in DNA damage repair defects and genomic instability." (PMID 38888809, 2024). "However, our study demonstrates that reducing PRC1 expression alters cancer cell characteristics and increases sensitivity to Doxo." (PMID 39409930, 2024). "Additionally, previous studies have demonstrated that PRC1 is associated with other key factors, including Wnt/β-catenin, polo-like kinase 1 (PLK1), and the p21/p27 family in various cancers." (PMID 39409930, 2024). "The caregivers were divided into two groups: PrC1, which included the primary caregivers of patients with non-oncological illnesses (n = 63), and PrC2, which included the primary caregivers of patients with malignancies (n = 77)." (PMID 39518011, 2024). "Differentially expressed genes (DEGs) associated with high (> median) PRC1 expression contribute to key signaling pathways related with cell cycle, DNA damage and repair, EMT, cell migration, invasion and cell proliferation in most cancer types." (PMID 37563591, 2023). "More specifically, the DEGs involved in RAS/RAF/MAPK, PI3K/AKT, WNT, NOTCH, TGF-β, integrin, EMT process, focal adhesion, RHO GTPase-related pathway or microtubule cytoskeleton regulation are upregulated when PRC1 expression is above median, as confirmed for most cancers." (PMID 37563591, 2023). "RNF2, the catalytic subunit of PRC1, is highly expressed in many different types of cancer." (PMID 35892678, 2022). "Pan-cancer analysis revealed the overexpression of PRC1 in the Cancer Genome Atlas (TCGA) database." (PMID 35983074, 2022). "We first accessed the pan-cancer expression of PRC1 in TCGA database." (PMID 35983074, 2022). "Although the majority of genes encoding for PRC1 subunits are not mutated in cancer, they are often deregulated." (PMID 36105358, 2022). "Overexpression of PRC1 components in cancer may influence its interacting partners and shift PRC1 homeostasis." (PMID 34316702, 2021). "Subsequently, immunohistochemical staining of xenograft tissues collected from nude mice demonstrated that knockdown of PRC1 could significantly inhibit the expression of cancer differentiation-related proteins (Cdc2, Cyclin B1, and ki67) (P < 0.05)." (PMID 33292244, 2020). "The deregulation of PRC1 contributes to tumorigenesis and cancer process." (PMID 33292244, 2020). "Numbers studies have reported the role of PRC1 in cancer development." (PMID 33292244, 2020). "The observation that PRC1 emerges as a high-confidence hit in two distinct cell lines, despite cancer type specificity and genetic variation, supports the relevance of our findings and suggests that the CDK16-PRC1 axis may be relevant in several cancer types." (PMID 30992425, 2019). "Recent studies showed that PRC1 was upregulated in many types of cancer and might serve as a prognostic biomarker of cancer." (PMID 30774662, 2019).